INS (insulin)
Diseases named in the same sentence as INS in open-access papers (continued):
Sharing a sentence is not in itself a finding about the gene and the disease.
type 2 diabetes (continued). "Moreover, individuals with Type 2 diabetes randomized to pioglitazone experienced improvements in insulin sensitivity in conjunction with increases in NP bioactivity, as determined by the expression of NP receptors in adipose tissue." (PMID 29758041, 2018). "Disruption of the normal insulin signaling cascade occurs in type 1 and type 2 diabetes." (PMID 30116147, 2018). "We investigated changes in the daily and day-to-day glucose variability and quality of life (QOL) related to insulin use in patients with type 2 diabetes during a switch from premixed insulin preparations comprising either human insulin (BHI30) or insulin aspart (BIAsp30) to IDegAsp twice daily." (PMID 30127860, 2018). "E. is a 61-year-old man with type 2 diabetes who has been treated with insulin for 20 years." (PMID 29682315, 2018). "Although these are the first PRO instruments developed based on perceptions of patients treated with non-insulin injectable medications for type 2 diabetes, there is overlap between these new instruments and instruments developed in samples of insulin-treated patients." (PMID 30294713, 2018). "Finally, it has been indicated that a single bout exposure to hypoxia can result in short term improvement in glycaemia control and the whole-body insulin sensitivity in individuals with type 2 diabetes, and the improvement can be maintained for 24–72 hours." (PMID 30199540, 2018). "About a quarter of the patients with type 2 diabetes use insulin." (PMID 29682315, 2018). "Interestingly, its expression is upregulated in insulin target tissues in rat models of type 2 diabetes." (PMID 29185012, 2018). "Requiring a registered diagnosis of type 2 diabetes, for those treated with non-insulin glucose-lowering medication, could have led to some degree of underestimation of incidence rates." (PMID 29995214, 2018). "Given that insulin-resistant subjects (either with obesity or type 2 diabetes) have elevated plasma FFA concentrations due to excessive lipolysis, TLR4 and downstream pathways in monocytes could be a mechanistic link between FFA and inflammation." (PMID 29649324, 2018). "Some insulin users with type 2 diabetes might have incorrectly reported type 1 diabetes, assuming that taking insulin meant they had type 1 diabetes." (PMID 29596402, 2018). "Therefore, reduction in the sex hormone binding globulin (SHBG) and high levels of free testosterone are accepted for the occurrence of diabetes type 2 and highlights the relationship between androgens and insulin sensitivity." (PMID 30647752, 2018). "Type 2 diabetes is a serious chronic metabolic disorder characterized by hyperglycemia, insulin resistance (IR), destruction of pancreatic beta cells and impairment in insulin secretion." (PMID 30110382, 2018). "However, injectable medications other than insulin are increasingly used to treat type 2 diabetes, including GLP-1 receptor agonists." (PMID 30294713, 2018). "Of note, while these studies relate ucOC to insulin sensitivity and Type 2 diabetes, ucOC does not appear to be associated with indices of glycemia in the setting of gestational diabetes and the role of ucOC in Type 1 diabetes remains uncertain." (PMID 29966260, 2018). "Other investigators have viewed ketosis-prone type 2 diabetes as a more severe form of type 2 diabetes in which the available insulin action at the cellular level is markedly impaired acutely but is partially reversible with appropriate treatment [2••, 4••, 5••, 12]." (PMID 30280274, 2018). "In this report, the authors demonstrated that overexpression of c-KIT in beta cells ameliorates glucose metabolism by increasing insulin secretion and thus implying that this receptor could have a protective role in preventing type 2 diabetes." (PMID 29795582, 2018). "Furthermore, the use of energy-restricted formula diets in obese persons with type 2 diabetes improved cardiometabolic endpoints, e.g., waist circumference, fat mass, blood pressure, insulin, or HbA1c." (PMID 30081574, 2018).
type 2 diabetes (continued). "Thus, fasting serum LCFA levels are correlated with long-term progressive deterioration of insulin secretion, as reported for Japanese patients with type 2 diabetes." (PMID 29921789, 2018). "In this study we propose a multi-level closed-loop model of whole-body glucose homeostasis, coupled with the molecular specifications of the insulin signaling cascade in adipocytes, under the experimental conditions of normal glucose regulation and type 2 diabetes." (PMID 29420588, 2018). "Notably, a 12 week exercise intervention in individuals with type 2 diabetes found an increased IMCL content with concomitantly increased insulin sensitivity." (PMID 29696296, 2018). "Lower insulin, and trends towards lower 120 min glucose level and lower HOMA2-IR among women in the exercise group, may indicate lower risk of developing type 2 diabetes." (PMID 29310617, 2018). "It has been suggested that vitamin D supplementation could affect insulin secretion and improve glucose homeostasis in obese people with type-2 diabetes." (PMID 30400199, 2018). "In addition, improved glucose tolerance and insulin sensitivity were found in a genetic mice model of type 2 diabetes treated by this extract." (PMID 29768504, 2018). "The goal of MITI was to provide a remote basal insulin titration program for patients with type 2 diabetes initiating or titrating basal insulin, utilizing the basic, low-cost, cell phone technology that most patients in safety-net clinics are already using: text messages and phone calls." (PMID 29555621, 2018). "The need to constantly titrate insulin dosage in order to maintain euglycemia was demonstrated in clinical studies which supervised frequent insulin titrations both in the context of type 1 and type 2 diabetes." (PMID 29682315, 2018). "In multivariate adjusted models, fasting insulin was no longer associated with incident type 2 diabetes." (PMID 29018885, 2018). "Meanwhile, the hypoglycemic effect induced by exercise training is probably due to the increased expression of IR, suggesting that ASE and exercise training exerts its antidiabetic effects by activation of different points of the insulin signaling pathway in type 2 diabetic rats." (PMID 29920546, 2018). "Despite the recent introduction of novel antidiabetic agents such as incretins and SGLT2 inhibitors and the more widespread use of bariatric surgery insulin therapy is ultimately required to maintain glycemic targets in a large proportion of severely obese patients with type 2 diabetes." (PMID 30114246, 2018). "Researchers have identified a protein, XBP1s, that may help treat type II diabetes by re-sensitizing cells to insulin." (PMID 30111834, 2018). "In type 2 diabetes (T2D), treatment with subcutaneous (SC) injections of long-acting basal insulin analogs is recommended as the first step when initiating insulin therapy even though postprandial hyperglycemia occurs early in disease progression due to the loss of early-phase insulin secretion." (PMID 29707584, 2018). "Early reports at the turn of the decade suggested that NAD levels are negatively impacted by high-fat diet and linked to type 2 diabetes (T2D), with NMN (a precursor to NAD) supplementation being capable of improving insulin sensitivity and glucose tolerance in a mouse model of T2D." (PMID 29581875, 2018). "Nevertheless, observations from this analysis may help guide combination treatment in people with type 2 diabetes who are on DPPIVi plus basal insulin therapy." (PMID 29370218, 2018). "Interestingly, many studieshave evaluated the addition of prandial insulin to the type 2 diabetic patients with improved control." (PMID 31404422, 2018). "Furthermore in patients with type 2 diabetes IL-1Ra improves glycemia, insulin secretion, and also fatigue." (PMID 29705519, 2018).
type 2 diabetes (continued). "Type II diabetes parameters also significantly changed with a decrease in HbA1c (0.8(−0.1–1.7) % (p < 0.05), fasting glucose (3.4(1.2–4.8) mmol/L (p < 0.001), and fasting insulin (69.2(27.8–190.4) pmol/L (p < 0.001)." (PMID 29110244, 2018). "Angptl4-deficient mice manifest greater insulin sensitivity and improved glucose homeostasis, further supporting for the conclusion that genetic inactivation of ANGPTL4 improves glucose homeostasis and reduces risk of type 2 diabetes." (PMID 29899519, 2018). "Obese women with PCOS are more insulin resistant and at higher risk of cardiometabolic diseases including type 2 diabetes than obese women without PCOS." (PMID 29324776, 2018). "Xu J, Rajaratnam R. Cardiovascular safety of non-insulin pharmacotherapy for type 2 diabetes." (PMID 29527102, 2018). "Collectively, these data suggest that APS could be a potential insulin sensitizer for the treatment of type 2 diabetes." (PMID 30347867, 2018). "This correlates with the increased pancreatic β-cell and serum insulin level as ACE inhibitors have been shown to be not just therapeutic against hypertension but also reduces the risk of type 2 diabetes and its complications." (PMID 29449808, 2018). "Moreover, type 1 diabetes is only treated by insulin whereas for type 2 diabetes a wide range of glucose-lowering medications is available, each being associated with a different risk of hypoglycaemia." (PMID 29717336, 2018). "Inclusion criteria were: type 2 diabetes, 18–75 years of age, glycosylated hemoglobin (HbA1c) more than 6.5% (48 mmol/mol) on multiple doses of insulin (MDI > four injections per day) or more than 100 units of insulin/day, wide glycemic excursions, and intractable hypoglycemia." (PMID 30410846, 2018). "It has been shown that metabolites produced when this pathway does not work properly can interfere with biological insulin activity causing insulin resistance, a hallmark of type 2 diabetes." (PMID 30271425, 2018). "Similarly, patients with type 2 diabetes display delayed early insulin secretion compared with that in healthy adults and are insulin resistant." (PMID 29629377, 2018). "IDE is the common link between AD and Type II diabetes as insulin is an IDE target as well." (PMID 30338033, 2018). "When using strict criteria for type 2 diabetes (clinician diagnosis of type 2 diabetes, age at diagnosis ≥ 35 years and insulin initiation ≥ 2 years from diagnosis, n = 203), 13% (95% CI 8.5, 18) of individuals meeting these criteria had C-peptide < 200 pmol/l." (PMID 28983693, 2018). "This could be relevant for type 2 diabetic patients and patients with metabolic syndrome, although the correlation of insulin resistance with the fat content of the liver is questionable." (PMID 29644441, 2018). "Consequently, in type II diabetes β-cells fail to secrete the insulin hormone and affect the skeletal muscle, liver, and adipose tissues." (PMID 29755552, 2018). "However, recently it has been shown that the second phase of insulin secretion is also impaired during type-2 diabetes." (PMID 29459424, 2018). "For MI as well as for the mortality outcomes, the risk reduction already at low consumption levels of 1–<2 servings/week was observed only among participants who had had type 2 diabetes less than 6 years, potentially indicating less severe/non-insulin treated disease." (PMID 28185684, 2018). "Glitazones represent an exception among antidiabetic drugs in that they target excess substrate metabolism and insulin sensitivity as pathogenic causes in the metabolic syndrome and type 2 diabetes as opposed to treating disease symptoms." (PMID 29973382, 2018). "Therefore, the purpose of this study was to conduct qualitative research to support the development of two new questionnaires focusing on patients’ perceptions of injection devices used with non-insulin treatments for type 2 diabetes." (PMID 30294713, 2018).
type 2 diabetes (continued). "Individuals with any susceptibility to glucose homeostasis alterations, such as reduced sensitivity to insulin, an impaired insulin response to glucose, first degree relatives with type 2 diabetes, obesity and older age, are more prone to develop GCs induced alterations." (PMID 30123187, 2018). "The cardiovascular safety of exogenous insulin therapy in type 2 diabetes is debated." (PMID 29402330, 2018). "Confirmation of insulin secretion and plasma glucose patterns in young healthy individuals might be helpful for early type 2 diabetes prevention." (PMID 29629377, 2018). "No studies in type 2 diabetes have demonstrated that structured education can lower the risk of severe hypoglycaemia in individuals with insulin-treated type 2 diabetes." (PMID 28660491, 2018). "Some studies revealed a negative relationship between Lp(a) and serum insulin; studies speculated that higher Lp(a) levels among patients with a longer duration of type 2 diabe­tes may be attributed to lower plasma insulin levels in individuals." (PMID 30254819, 2018). "Importantly, higher levels of saturated fatty acids such as palmitate impair insulin signaling in skeletal muscle by induction of systemic lipotoxicity, with subsequent development of type 2 diabetes." (PMID 29875018, 2018). "Further, the impact of familial risk on insulin secretion, insulin action and type 2 diabetes has not been studied and compared across populations of Middle Eastern and European ancestries, which is the aim of this study to investigate." (PMID 29274011, 2018). "As it was demonstrated that resveratrol improves insulin sensitivity by activating AMPK, many later studies have evaluated the use of the polyphenol in the management of glucose control and in type 2 diabetes mellitus, the risk of which is increased under the persistence of glucose intolerance." (PMID 30400297, 2018). "The study was started with 45 patients with type 2 diabetes (insulin independent), but 40 patients (15 in the control group [8 males and 7 females], 13 in the aerobic group [7 males and 6 females], and 12 in the weighted vest group [7 males and 5 females]) completed the study." (PMID 30483312, 2018). "Pandya N, DiGenio A, Gao L, Patel M. Efficacy and safety of insulin glargine compared to other interventions in younger and older adults: a pooled analysis of nine open-label, randomized controlled trials in patients with type 2 diabetes." (PMID 29527102, 2018). "Rye products have been reported to elicit postprandial insulin and glucose responses which may be beneficial for prevention of type-2 diabetes." (PMID 28417207, 2018). "In this study, we investigated changes in the daily and day-to-day glucose variability and quality of life (QOL) related to insulin use in patients with type 2 diabetes in a real-world setting who switched from BHI30 or BIAsp30 twice daily to IDegAsp twice daily." (PMID 30127860, 2018). "S. is a 62-year-old woman with type 2 diabetes who has been treated with insulin for 15 years." (PMID 29682315, 2018). "A short-term treatment with UAG improved insulin sensitivity in patients with Type 2 diabetes." (PMID 29320575, 2018). "One study examined the correlation between fasting C-peptide and glucose variability (CGM SD) and found inverse associations in both type 1 diabetes and insulin-treated type 2 diabetes, although hypoglycaemia was not examined." (PMID 28983693, 2018). "Furthermore, patients with type 2 diabetes who lost weight following a dietary intervention demonstrated decreased PP, increased insulin secretion, and increased glucose sensitivity." (PMID 28753646, 2017). "Furthermore, A.lappa 200 mg/kg treated diabetic mice revealed a significant increase in insulin level as compared to type 2 diabetes group (p<0.05)." (PMID 28348972, 2017). "In conclusion, these results suggest that AGE might play a role in the development or prediction of insulin secretory defects in type 2 diabetes." (PMID 28695132, 2017).
type 2 diabetes (continued). "Furthermore, during the progression of normal glucose tolerance to IFBG and type 2 diabetes, insulin production has been found to decrease more rapidly in African populations than in European populations." (PMID 28144712, 2017). "Discussion and conclusion: These findings indicate that ES3 and its fatty acid-rich fraction exhibit antidiabetic activities in insulin-responsive cell lines and may hence prove useful for the treatment of type 2 diabetes." (PMID 28112007, 2017). "Characterization of insulin exocytosis offers insights into the role that elevated cholesterol may play in the development of type 2 diabetes." (PMID 28544529, 2017). "Type 2 diabetes results from defects in both insulin sensitivity and insulin secretion." (PMID 28842702, 2017). "However, the significant more representation in this study of subjects affected by type 1 diabetes, respect to those affected by type 2 diabetes, reflects what is generally observed in clinical samples of insulin-treated subjects." (PMID 28724422, 2017). "Another paradigm for such disorders, type 2 diabetes (T2DM) is shown to be an important risk factor for both PD and AD, and methods to favorably manipulate insulin signaling pathways and related molecules has shown tremendous interest and some early clinical success." (PMID 28649604, 2017). "Some experimental studies have shown that reduction of the extracellular pH decreases beta cell response, reduces insulin secretion and increases cortisol production, which in turn may affect the development of type 2 diabetes." (PMID 27858141, 2017). "Moreover, we also showed that insulin triggers CB activation, suggesting that hyperinsulinemia may be one of the stimulus responsible for CB overactivation leading to sympathetic nervous system overactivity that is associated with metabolic disturbances, such as type 2 diabetes." (PMID 29311923, 2017). "Participants developing type 2 diabetes also exhibited higher blood pressure, heart rate, BMI and waist circumference, fasting insulin and HOMA-R index, and more abnormal lipid profile (lower levels of HDL-cholesterol and higher triglycerides) than those remaining in the non-diabetic range." (PMID 28499385, 2017). "Consider initiating insulin therapy (with or without additional agents) in patients with type 2 diabetes who remain markedly symptomatic (weight loss, ketosis, polyuria, or polydipsia) and/or exhibit elevated blood glucose levels or HbA1c." (PMID 28725272, 2017). "Polyphenols may influence glycemia and type 2 diabetes (T2D) through different mechanisms, such as promoting the uptake of glucose in tissues, and therefore improving insulin sensitivity." (PMID 28883903, 2017). "Our data suggest that insulin treatment could attenuate the progression of sarcopenia in patients with type 2 diabetes." (PMID 28246927, 2017). "Type 1 diabetes is characterized by a lack of insulin production in the pancreas, while type 2 diabetes is caused by inefficient use of insulin in the body and has been associated with obesity and a sedentary lifestyle." (PMID 28718928, 2017). "Normal insulin signalling is perturbed in diabetic patients, where either insulin can’t be produced (type 1 diabetes) or the cellular response to insulin doesn’t function correctly (type 2 diabetes)." (PMID 29257048, 2017). "The role of the endoplasmic reticulum–mitochondria junction in coordinating the functions of these two organelles throughout the natural history of type 2 diabetes is determinant and may explain the alterations of insulin biosynthesis." (PMID 28742858, 2017). "Each cluster was annotated with the enriched functions of the corresponding gene set, such as glycolysis/gluconeogenesis, adipocytokine signaling pathway, and PPAR signaling pathway which improves glycemic control, lipid metabolism, and insulin sensitivity in type 2 diabetes." (PMID 28837146, 2017).